RN7SKP183 (RN7SK pseudogene 183)
Gene: Miscellaneous RNA gene on chromosome X (20,452,108 to 20,452,431, forward strand). Ensembl gene ENSG00000252978.
Homologues: Orthologues: chimpanzee 7SK (99% identical), guinea pig 7SK (48% identical). Paralogues in human: RN7SKP124 (54% identical), RN7SKP249 (53% identical), RN7SKP180 (52% identical), RN7SKP162 (52% identical), RN7SKP127 (51% identical), RN7SKP79 (51% identical), RN7SKP184 (51% identical), RN7SKP208 (51% identical), RN7SKP225 (51% identical), RN7SKP165 (51% identical), RN7SKP176 (50% identical), RN7SKP214 (50% identical), and 284 more.